IL1B (interleukin 1 beta)
Diseases named in the same sentence as IL1B in open-access papers (continued):
Sharing a sentence is not in itself a finding about the gene and the disease.
tumor (continued). "Ongoing clinical trials of COX-2/PGE2 pathway inhibitors targeting the major COX-2 inducer IL-1B, COX-2 itself, or the PGE2 receptors EP2 and EP4 present new opportunities to promote anti-tumor activity, but may also have the potential to enhance the severity of ICB-induced irAEs." (PMID 38443917, 2024). "In the human PDAC patient tumor transcriptome (TCGA), we identify strong and significant correlations between tumoral GHR expression and known lymphangiogenic (LYVE1, FLT4, VEGFC, and PDPN) and angiogenic (PDGFRa, FGFR1, TGFB3, TGFB1, TGFBR2, HIF1a, IL6, and IL1B) markers." (PMID 39000545, 2024). "Our study found a significant decrease in IL-6, IL-1β, IL-17A, and TNF-α levels in mice after L.p CMU-Pb-L5 intervention, indicating that L.p CMU-Pb-L5 intervention could reduce inflammatory cytokine levels in vivo and slow CRC tumor growth." (PMID 39439459, 2024). "In the tumor microenvironment, IL-1β may be produced and regulated at the site of the tumor, leading to elevated mRNA expression without a corresponding increase in plasma levels." (PMID 39766795, 2024). "However, our study did not examine the effects of tumor-secreted IL-1β on TIBs or other immune cells." (PMID 39801513, 2024). "Furthermore, the highest level of IL1B expression was observed in macrophages in ccRCC samples, and spatial transcriptome analysis revealed the colocalization of VEGFA+ MCs with IL1B+ macrophages at the tumor–normal interface." (PMID 39840068, 2024). "These three signatures consist of myeloid-focused cytokines (TNFa, GM-CSF, and IL-1b), chemokines (CCL3, CCL4, CCL5, CXCL9, and CXCL10), and an effector T-cell-derived cytokine (IFNg) and represent important aspects of a macrophage-based anti-tumor immune response." (PMID 39199551, 2024). "Furthermore, VCN-AgNPs increased the apoptotic proteins Bax and caspase-3, decreased the anti-apoptotic protein (Bcl-2), increased the inflammatory markers TNF-α and IL-1β, and inhibited angiogenesis by lowering VEGF levels in tumor tissues, all of which led to apoptosis." (PMID 39513869, 2024). "In addition, there was no change in tumour gene expression of proinflammatory cytokines (Tnfa, Il1b, Il6 and Osm) between untreated and AR‐treated C26 mice." (PMID 38572511, 2024). "Similarly, IL1b higher transcript level was revealed in both age groups (≤ 60 and > 60) and locations (larynx and oral cavity) in men but not women, in all histologic grade stages (G1-G3) and T3-T4 and N0, N2 TNM tumor stages." (PMID 38175424, 2024). "We show that NT GSDMD electroporation does not lead to a decrease in tumor growth, not even when pyroptosis was enriched with IL-1β pretreatment and all animals were rapidly eliminated demonstrating that the protective effects of pyroptosis and cytokine-armed pyroptosis depend on the immune system." (PMID 39737979, 2024). "Interestingly, tumor or malaria infection did not significantly alter the serum level of IL-1β and TNF-α." (PMID 38774541, 2024). "Moreover, elevated levels of pro-inflammatory factors TNF-α, IL-1β, and IL-6 in the serum of LLC tumor-bearing mice could be detected by ELISA assay, whereas UA could obviously reduce the concentration of inflammatory factors in a dose-dependent manner." (PMID 37190306, 2023). "Although using anti‐IL‐1β antibody alone could not ameliorate tumor growth, the addition of anti‐IL‐1β antibody significantly enhanced the anti‐tumor effect of anti‐PD‐1 antibody." (PMID 37092583, 2023). "Furthermore, NLRP3 inflammasome may also influence the anti-tumor immune response in LCE patients, as IL-1β can enhance the recruitment and activation of natural killer cells and cytotoxic T cells, which can eliminate tumor cells." (PMID 37715239, 2023). "Interestingly, treatment of the “negative” tumor cells with WGA or MAA triggered an increase in IL1β, IL6, IL8 and/or MIP1β secretion(lines with negative impact in red)." (PMID 36891308, 2023).
tumor (continued). "Finally, the mechanism by which combined stimulation with IL-1β and IFN-γ specifically activates MAPK signaling in tumor cells remains unknown." (PMID 37441079, 2023). "ZBSO inhibited tumor growth in vivo without down-regulating TNF-α or IL-1β." (PMID 37081962, 2023). "The elevated neutrophil-to-lymphocyte ratio in the TME during neoadjuvant chemotherapy could impair its anti-tumor efficacy due to upregulated neutrophil-CAFs-tumor cell IL-1β/IL-6/STAT-3 signaling, showing a poor/absent response." (PMID 37173915, 2023). "We propose that, at the primary location, OC cells can release specific cytokines (i.e., IL-6, IL-8, IL-1β, G-CSF, GROα, MCP-1, and TNFα) to the tumor environment (i.e., peritoneal fluid) which may attract neutrophils to pro-metastatic niches (for instance, omentum) to induce NETosis." (PMID 36983067, 2023). "M2-type macrophages, TAMs and cancer cells can stimulate IL-1β production and subsequently, IL-1β increases macrophage recruitment through the expression of monocyte chemoattractant protein (MCP)-1, which can be polarized into TAM and promote cancer, tumor growth, and metastasis." (PMID 36835413, 2023). "However, in our animal model and in human brain metastatic tissue, no IL-1β expression was detected in tumor cells." (PMID 37749707, 2023). "In summary, our findings demonstrate a protumorigenic function of IL-1β in PDGFB-driven mGBM and show that blocking IL-1β signaling decreases inflammatory monocyte recruitment, MG abundance, and the frequency of exhausted CD8+ T cells, prolonging survival of tumor-bearing mice." (PMID 37733448, 2023). "Even though the region of interest (ROI) selection was random and did not cover the entire tumor, it should be appreciated that direct delivery of anti–IL-1b antibodies and IL-1Ra into the tumors resulted in only local inhibition due to limited antibody diffusion." (PMID 37733448, 2023). "Surprisingly, despite the presence of cytosolic DNA or exogenous DNA transfection, epithelial cancer cells do not produce appreciable amounts of IL-1β compared to myeloid THP-1 cells, implying that the IL-1β in the tumor microenvironment does not originate from the tumor cells themselves." (PMID 37449203, 2023). "According to the scRNAseq results, IFNγ and IL1β/TNFα are necessary to induce the highest levels of NOS2 and COX2 expression, which suggests that lymphoid cells could be a contributing factor in the tumor." (PMID 37169743, 2023). "Notably, the secreted IL-1β/IL-18 activates downstream signaling pathways by binding to their respective receptors (IL1R1, IL-18Rα, and IL-18Rβ) on tumor cells, therapy performing multiple functions in tumor progression." (PMID 36823153, 2023). "In TME or TIME infiltrated B cells under the influence of IL-6, IL-1β, IL-12p35, and low oxygen (tumor-promoting molecules), which polarize to regulatory B cells (Bregs), producing TGF-β, granzyme B (GZMB), IL-10, and IL-35, which promote tumor growth and metastasis." (PMID 37275901, 2023). "Therefore, the large size of tumor spheres in LPS/ATP-treated MDA-MB-231 cells could be explained by hypoxia, indicated by the high SCGF-b and IL-1β secretion level." (PMID 36902278, 2023). "Furthermore, IL-1β was identified as a promoter of vascular endothelial growth factor (VEGF) and C-X-C motif chemokine ligand 2 (CXCL2) expression, which are both crucial for tumor growth and metastasis." (PMID 38066523, 2023). "However, IL-1β production elicited by anti-tumor agents from various cell subsets in TME is not always beneficial." (PMID 36932407, 2023). "RA may also contribute to tumor proliferation through the secretion of IL-6, TNF- α, and IL-1β." (PMID 37876939, 2023). "In addition, we also found that tumor-bearing mice-derived CD11B+ DCs and monocytes secreted higher level of IL-1β compared with those from control mice after being stimulated with LPS, whereas CD11B− DCs showed comparable levels of IL-1β from both control and tumor-bearing mice." (PMID 37400621, 2023).
tumor (continued). "However, both IL-6 and IL-1β levels were still elevated in the RT and COMB groups, which might have resulted in the higher cleaved caspase-3 level and better tumor inhibition seen in these two groups." (PMID 37242761, 2023). "Furthermore, we found that the levels of pro-inflammatory factors TNF-α, IL-1β, and IL-6 in the serum of LLC tumor-bearing mice lowered by UA could be raised by Ex-527 treatment." (PMID 37190306, 2023). "Similar results were obtained in vivo where the elevated expression of IL-6 (approximately twofold), IL-1β (threefold), and TNF-(sixfold) was observed (the expression of the stated inflammatory markers was evaluated in XM-S and XM-R mouse models after 21 days of tumor induction)." (PMID 36840009, 2023). "Furthermore, calcitriol amplified the levels of the negative regulators of the Wnt/β-catenin pathway TCF7L2 (encoding TCF4), DKK1, and AXIN1; it also antagonised the pathway by reducing the production of IL-1β by TAMs, inhibiting GSK-3β activity in tumour cells, and increasing β-catenin expression." (PMID 37299554, 2023). "Furthermore, pharmacologic inhibition of NF‐κB activation (BAY11‐7085) dampened the IL‐1β‐induced upregulation of PD‐L1 transcription in all three tumor cell lines, while ERK inhibition (SCH772984) did not work." (PMID 37009412, 2023). "While chronic inflammation promotes tumor progression, tumor cells themselves also attract immune cells via chemokines such as IL-8, CCL2 (MCP-1), CCL3 (MIP-1α), CCL5 (RANTES), CXCL6 (huGCP-2), and cytokines such as IL-1β, IL-6, TNFα, GM-CSF, and G-CSF, inducing inflammation." (PMID 36614196, 2023). "However, we found that Il1b knockout didn’t affect primary tumor growth in HCC xenografts, suggesting that Il1b may promote the malignant transformation of hepatocyte into HCC without affecting the outgrowth of advanced HCC." (PMID 37443052, 2023). "Inhibition of Notch signaling not only promoted the cytotoxicity of tumor-infiltrating CD8+ T cells, but also enhanced CD8+ T cells’ production of proinflammatory cytokines [including IFN-γ, tumor necrosis factor alpha-like (TNF-α), interleukin-1 beta (IL-1β), IL-6, and IL-8] in those patients." (PMID 37131214, 2023). "On day 10 post tumor challenge, when levels of the three pro-inflammatory cytokines were still low, we began injections of validated blocking antibodies targeting TNFα, IL-1β, IL-6R, or no blockade." (PMID 37461742, 2023). "Tumor-derived long intergenic non-coding RNA-482 (LINC00482) was shown to increase levels of pro-inflammatory cytokines such as IL-6, tumor necrosis factor alpha (TNFα), and IL-1 beta (IL-1β), as well as VEGF, which led to increased inflammation and angiogenesis." (PMID 37569686, 2023). "It is known that KPF modulates the expression and activation of IL-1β and TNF-α and the NF-kB pathway is activated by TNF-α to promote tumor cell proliferation and the inhibition of apoptosis, and that it enhances the tumor angiogenesis ability and the potential of invasion and metastasis." (PMID 37445894, 2023). "Following in vivo interaction of CAR T- and tumor cells, CAR T-cells liberate inflammatory cytokines (e.g., TNF-α and IFN-γ), leading to the hyperactivation of macrophages and the secretion of large amounts of IL-6 and IL-1β, which can be effectively abolished by the use of corticosteroids." (PMID 36830750, 2023). "Propofol decreased hypoxia inducible factor 1α (HIF1α), interleukin 1β (IL1β), and hepatocyte growth factor (HGF) gene expressions and increased tissue inhibitor of metalloproteinases 2 (TIMP-2) gene and protein expression in comparison to sevoflurane in the tumour tissue." (PMID 35953652, 2023). "Compared with that in tumours, the increase of IL-1β, IL-18, and HMGB1 levels in the serum was not severe, suggesting that TIOs+NIR3-triggered antitumour immune response is relatively safe and does not cause hyperactive immune response or substantial systematic inflammation." (PMID 37673934, 2023).
tumor (continued). "IL-1β and IL-17A are known to negatively regulate Regnase-1 and we found significant upregulation of IL-1β but did not detect IL-17A expression in the tumor sites." (PMID 37814340, 2023). "The tumor vasculature primarily comprises endothelial cells, playing a critical role in tumor growth and facilitating immune reactions within the TME through the release of various neuroimmune substances, including IL-1β, IL-10, and granulocyte-macrophage colony-stimulating factor (GM-CSF)." (PMID 37533851, 2023). "However, no effective and non-invasive methods to detect IL1B expression in HNSCC tumor currently exist, other than surgical procedures combined with pathological examinations." (PMID 36969073, 2023). "Similarly, in the MC38 hot tumor mouse model, CCL20 and IL-1β also drove ILC3s infiltration and lymphocytes recruitment to inhibit tumor growth and also enhanced the reactivity to ICB including anti-PD-1 and anti-CTLA-4, significantly extending the survival rate." (PMID 37122757, 2023). "In addition, cytokines TNF-α, IL-6, IL-1β, and IFN-γ are involved in the adhesion of circulating MSCs to the vascular endothelial layer, and MSCs adhering to the vascular endothelial layer enter tumor tissue through the vascular wall." (PMID 37666813, 2023). "Notably, IL1B upregulation persisted after LSP + MET treatment, a phenomenon that might also control tumor growth, as a pyroptotic type of cell death via the cGAS-STING pathway was triggered by persistent stimulation of IL1β." (PMID 36765551, 2023). "Finally, NRPP inhibited tumour growth and downregulated the levels of TNF‐α, IL‐1β and IL‐6." (PMID 37610095, 2023). "This evidence, together with the results of our study, supports the hypothesis that piperine may have bound to these mediators, preventing the binding of IL-1β to its receptor and the synthesis of PGE2, and resulting in an anti-inflammatory and antitumor effect in the tumor cells." (PMID 36678600, 2023). "To further demonstrate the altered microbiota contributed to the enhanced IL-1β secretion, we sorted the LP CD11B+CD11C- monocytes, CD11B-CD11C+ dendritic cells, and CD11B+CD11C+ dendritic cells from WT mice and stimulated with fecal contents isolated from mock or tumor-bearing mice, respectively." (PMID 37400621, 2023). "CAR-M recruited CD3 T cells and reduced PD-L1+ cells at the tumor site—confirming that the engineered Mφ was not the only driver of the anti-tumor response—and increased serum levels of the inflammatory cytokines IL-1β, IL-6, and TNF-α, demonstrating a systemic immune response." (PMID 38139461, 2023). "EPA treatment inhibited the mRNA expression of inflammatory cytokines including IL-1β, IL-6, MCP-1, and TNF-α in both the CaOV3 and SKOV3ip tumors, which was validated by similar decreased levels of these inflammatory cytokines in the serum from mice of both tumor models." (PMID 35326656, 2022). "Thus, our data indicates that caspase-4 functions in the arrest in cell proliferation is independent of its downstream effect on IL-1β activation, suggesting a split in tumor suppressive and proinflammatory functions." (PMID 34916628, 2022). "MDSC is mainly regulated by factors secreted by tumor cells, such as stem cell factor(SCF) and vascular endothelial growth factor(VEGF) which increase the number of MDSCs and inflammatory cytokines and chemokines such as IL-4, IL-6, IFN-γ, and IL-1β which suppress MDSC." (PMID 36237303, 2022). "When constructing mouse models, we found that during this process, extensive infiltration of Bregs increased the expression of IL-1β and decreased the activity of CD8+ T cells, promoting tumorigenesis, while reverse expression of PD-L1 and IL-35 in Bregs supported immune escape of tumor cells." (PMID 35965504, 2022).
tumor (continued). "The increased expression of proinflammatory cytokines (IL-6, TNFα, IL-1B) found here in the aggressive PCa-related PPAT supports the role of PPAT in aggravating the tumor microenvironment, either by direct effects on premalignant cells or by acting on the tumor microenvironment." (PMID 35978404, 2022). "To further determine whether ATO regulates IL-1β secretion by modulating macrophage function, we measured ICAM1 levels in HNSCC cells after combinatorial treatment with ATO and CM or the addition of ATO to the THP-1–tumor cell coculture system." (PMID 36264639, 2022). "A comparison of chemical-induced tumor incidence in mice lacking expression of IL-1RI ligands revealed that IL-1Ra expression strongly protects from tumors, IL-1α had a weak protective effect, whereas IL-1β strongly supports tumor development." (PMID 36293159, 2022). "Here, we showed how deltarasin functions to abrogate a mutant KRAS-initiated in vivo inflammatory loop of tumor-derived CCL2 and myeloid-secreted IL-1β by downregulating the IL1R1 expression of KRAS-mutant tumor cells and thereby abolishing their receptivity to myeloid IL-1β signals." (PMID 35327394, 2022). "In addition, OC cells overexpressed plasminogen activator inhibitor-1 (PAI-1) and transcription factor DLX4 to induce the expression of IL-8/CXCL5 and IL-1β/CD44 via activating NF-κB signaling, further enhancing tumor-mesothelial cell interactions and facilitating the metastasis." (PMID 36268019, 2022). "To explore a mechanistic link between tumor-infiltrating neutrophils and iCAF-mediated IL-6/STAT-3 signaling in the PDAC TME, we characterized the secretome of tumor-infiltrating Ly6G+F4/80- neutrophils isolated from orthotopic KPC tumors, revealing IL-1β as the most robustly secreted cytokine." (PMID 36107485, 2022). "Furthermore, NGS analysis revealed that NF-κB/RELA targets including CCL2, CXCL8, EDN1, IL-1β, IL-6, and SERPINE1 were further reduced and several potential tumor suppressors, such as FABP3, FADS2, FDFT1, SEMA6A, and PCK2, were synergistically induced by the Gefitinib-+IKK16 treatment." (PMID 36358633, 2022). "IL-1β secreted by tumor-activated monocytes promoted the development of IL-17–producing CD8+ T-cell (Tc17) populations and the supernatants induced the production of the chemokine CXCL12 by tumor cells and led to functional impairment of antitumor CD8+ cytotoxic T-cells." (PMID 35382168, 2022). "Mature DCs can first secret IL-1β, IL-2, IL-6, TNF-α, and IFN-γ to promote the differentiation of T cells into CD8+ subset and then activate those CD8+ T cells to CTLs through the cross-presentation of tumor antigen peptides with major histocompatibility complex class I (MHC I)." (PMID 35836249, 2022). "Additionally, IL-1β can upregulate hypoxia-inducible transcription factor-1α(HIF-1α), which transcripts VEGF and COX-2 and promotes angiogenic activity, thus providing a microenvironment favorable for tumor growth in bone metastatic sites." (PMID 36237303, 2022). "In addition, studies of IL-1β, IL-11, IL-17, IL-18, and TNF also indicate that proinflammatory cytokines are key regulators for TME in inhibiting tumor cell proliferation, reducing inflammation, and preventing tumor metastasis." (PMID 35069767, 2022). "Using in vitro and in vivo models, we have attempted to identify these inhibitors that could prevent IL1β-driven bone metastasis without stimulating tumour growth outside the bone or adversely affecting systemic immunity." (PMID 36230739, 2022). "To elucidate mechanisms through which IL-1β promotes tumor progression, we analyzed bronchoalveolar lavage fluids (BALFs) and whole lungs of CC-LR mice with or without IL-1β blockade to investigate the effects on tumor-infiltrating immune subsets within the TME." (PMID 35471938, 2022). "Thus, knockdown of IL-1β and CCL7 etc. were insufficient to inhibit tumor invasion." (PMID 36045118, 2022).